ASS1 (argininosuccinate synthase 1)
Diseases named in the same sentence as ASS1 in open-access papers (continued):
Sharing a sentence is not in itself a finding about the gene and the disease.
atherosclerosis (3 papers, 2024 to 2025). A disease characterized by the build-up of fatty material and calcium deposition in the arterial wall resulting in partial or complete occlusion of the arterial lumen. "In T2D, reduced ASS1 expression impairs nitric oxide production, causing endothelial dysfunction and complications like atherosclerosis and diabetic nephropathy." (PMID 40370100, 2025). "In summary, our study has provided new insights into the role of endothelial SIRT3 in maintaining vascular homeostasis and preventing atherosclerosis through SIRT3‐mediated deacetylation of ASS1, which is responsible for de novo arginine biosynthesis." (PMID 38233193, 2024). "Therefore, using the endothelium selective Sirt3 knockout mice, we performed a more comprehensive study on the detailed role of SIRT3 in EC function during atherosclerosis and demonstrated that ASS1‐dependent arginine biosynthesis as a target of SIRT3 in EC." (PMID 38233193, 2024). "Without SIRT3, impaired ASS1 activity and L‐arginine deficiency are critical factors contributing to mitochondrial dysfunction, disturbance of NO and redox status, endothelial inflammation, and enhanced atherosclerosis induced by SIRT3 deletion in mice." (PMID 38233193, 2024). "This study provides compelling evidence supporting the protective role of endothelial SIRT3 in atherosclerosis and also suggests a critical role of SIRT3‐induced deacetylation of ASS1 by ECs for arginine synthesis." (PMID 38233193, 2024). "Notably, ASS1 and DDAH1 also contribute to the regulation of vascular NO production to prevent inflammatory processes such as atherosclerosis." (PMID 38894980, 2024).
breast tumor (3 papers, 2021 to 2025). "We found that breast tumors with elevated ASS1 expression exhibited greater abundance of CAFs and immune cells compared with tumors expressing low ASS1." (PMID 41511309, 2025). "Furthermore, the weight of breast tumor xenografts in derived from ASS1 knockout cells significantly increased, but the weight of breast tumor xenografts derived from PHGDH knockout cells decreased greatly relative to that of control cells." (PMID 38710705, 2024). "Compared to control cells, ASS1 knockout greatly enhanced the growth of xenograft breast tumors, whereas PHGDH knockout largely inhibited the growth of xenograft breast tumors." (PMID 38710705, 2024).
cyst (3 papers, 2023 to 2025). A sac-like closed membranous structure that may be empty or contain fluid or amorphous material. "Moreover, ASS1 immunostaining of mouse kidney samples indicated high expression in Tsc1 KO kidneys, specifically in cyst-lining epithelial cells." (PMID 37290438, 2023). "Glutamine dependence in ADPKD, investigated by the ASS1 pathway, with urea production in mice and human ADPKD tissue, showed that arginine depletion induced cyst reduction." (PMID 38541041, 2024). "Given the observed downregulation of ASS1 in ADPKD cyst-lining cells, similar to clear-cell renal cell carcinoma, arginine deprivation could potentially impair cyst growth and progression." (PMID 40722668, 2025).
endothelial dysfunction (3 papers, 2014 to 2025). In vascular diseases, endothelial dysfunction is a systemic pathological state of the endothelium (the inner lining of blood vessels) and can be broadly defined as an imbalance between vasodilating and vasoconstricting substances produced by (or acting on) the endothelium. "Interestingly, inhibition of either ASS1 or ASL in ECs has been shown to result in decreased NO production, endothelial dysfunction, and vascular inflammation." (PMID 38233193, 2024).
malignant mesothelioma (3 papers, 2021 to 2024). A malignant neoplasm of the pleura or peritoneum, arising from mesothelial cells. "Exogenous arginine is crucial for ASS1-deficient cancers, and malignant mesothelioma has an auxotrophic dependency on arginine in which exogenous arginine deprivation induces apoptosis of malignant mesotheliomas cells with ASS1 loss." (PMID 38610930, 2024).
neuroblastoma (3 papers, 2022 to 2025). Neuroblastoma (NB) is the most common solid, extracranial childhood tumor. "PHGDH expression was enhanced in neuroblastoma cells with ASS1 deficiency treated with arginine deiminase, with a concomitant enrichment of intracellular serine and glycine and downregulation of the Warburg effect." (PMID 36319669, 2022). "Both recombinant arginine deiminase and ADI-PEG20 reduced ASS1-deficient neuroblastoma cell proliferation in a dose-dependent manner." (PMID 36319669, 2022). "We found that a combination of recombinant arginine deiminase or ADI-PEG20 and CBR-5884 synergistically reduced the viability of ASS1-deficient neuroblastoma cells." (PMID 36319669, 2022). "Inhibiting the arginine metabolism, which is closely related to serine metabolism using arginine deiminase, had a combination effect both in vitro and in vivo, especially on extracellular arginine-dependent neuroblastoma cells with ASS1 deficiency." (PMID 36319669, 2022). "Neuroblastomas are often arginine auxotrophic, with tumors exhibiting high arginase activity and low ASS1 expression." (PMID 40813699, 2025). "To investigate the combinational treatment of PHGDH inhibition and arginine depletion in neuroblastomas, we confirmed ASS1 expression levels in neuroblastomas and their correlation with PHGDH expression levels." (PMID 36319669, 2022). "We demonstrated that ADI-PEG20, a pegylated arginine deiminase, almost halted the growth of neuroblastoma cells with ASS1 deficiency and reduced the growth of those without ASS1 deficiency for 2 weeks in vivo." (PMID 36319669, 2022). "The combinational therapy was also effective for IMR-32 cells, i.e., neuroblastoma cells without ASS1 deficiency, particularly in vivo." (PMID 36319669, 2022). "Combining these two drugs could be potentially effective for a wide variety of neuroblastomas, irrespective of the presence or absence of ASS1 deficiency." (PMID 36319669, 2022). "While ASS1 expression did not correlate with BCT-100 IC50 in neuroblastoma cell lines, upregulation of ASS1/ASL/OTC was observed in some BCT-100 treated Th-MYCN tumors." (PMID 40813699, 2025). "In contrast, with normal ASS1-expressing neuroblastoma cells exhibited only mild to no response to arginine depletion." (PMID 36319669, 2022). "BCT-100 is thus active against neuroblastoma cells irrespective of ASS1 expression." (PMID 40813699, 2025).
pancreatic ductal adenocarcinoma (3 papers, 2017 to 2021). An infiltrating adenocarcinoma that arises from the epithelial cells of the pancreas. "The goal of this study was to evaluate the prognostic impact of ASS1 expression in patients with pancreatic ductal adenocarcinoma (PDAC)." (PMID 28187218, 2017).
pulmonary fibrosis (3 papers, 2022 to 2025). Chronic progressive interstitial lung disorder characterized by the replacement of the lung tissue by connective tissue, leading to progressive dyspnea, respiratory failure, or right heart failure. "Recently it was reported that ASS1 deficiency happened in pulmonary fibrosis, MET can be activated by knocking down ASS1, then interacting with the upstream of the Src-STAT3 signaling to up-regulate the proliferation of fibroblast cells." (PMID 36147332, 2022). "In summary, targeting inositol-related metabolic and signaling pathways driven by ASS1 deficiency represent an effective approach to halt lung fibrosis, and our study offers evidence of inositol supplementation as a viable and potential therapeutic avenue for IPF." (PMID 37194070, 2023). "To develop a novel strategy to target arginine-dependent pulmonary fibrosis, we have conducted metabolomics studies and characterized the metabolic landscape of fibrotic lung fibroblasts mediated by ASS1." (PMID 37194070, 2023). "Furthermore, our transcriptomic work shows that ASS1 is highly expressed in pathologic fibroblast populations from pulmonary fibrosis patients." (PMID 40454944, 2025).
Alzheimer disease (2 papers, 2008 to 2024). A progressive, neurodegenerative disease characterized by loss of function and death of nerve cells in several areas of the brain leading to loss of cognitive function such as memory and language. "Among the up-regulated genes, ASS1 expression levels were significantly higher in glial cells of Alzheimer's disease brains." (PMID 19102749, 2008). "Our bioinformatics analysis revealed four key differential genes—ASS1, HDAC2, SIRT3, and VEGFA—as Co-DEGs in patients with Alzheimer’s disease (AD) and OSA." (PMID 39081807, 2024).
astrocytoma (2 papers, 2021).
Breast invasive carcinoma (2 papers, 2013 to 2023). "We can also observe that Q138Rfs*2/Pfs*12 alteration was detected in cases of STAD, BRAC (Breast invasive carcinoma), and COAD, which could induce a frameshift mutation of the ASS1 gene, translation from Q (Glutarnine) to R (Arginine) or P (Proline) at the 138 locus of ASS1 protein." (PMID 38053661, 2023).
colorectal tumors (2 papers, 2020 to 2022). "ASS1 is also highly expressed in colorectal tumors and can be used as a target in human primary colorectal tumors." (PMID 35674458, 2022). "The application of ASS1 inhibitors or ASS1 knockout weakens the pathogenicity of colorectal tumors." (PMID 35674458, 2022).
cutaneous melanoma (2 papers, 2022). A primary melanoma arising from atypical melanocytes in the skin. "Single agent recombinant, pegylated ADI‐PEG20 (ADI; pegargiminase) has efficacy with low toxicity in clinical trials in ASS1‐deficient tumours including hepatocellular carcinoma, mesothelioma and cutaneous melanoma." (PMID 35466524, 2022). "Although ASS1 demethylation may be involved, as noted in an earlier study in cutaneous melanoma, c‐myc may be also a potential driver of ASS1 upregulation under arginine depletion in UM." (PMID 35466524, 2022).
lymph node metastases (2 papers, 2017 to 2025). "All ASS1-loss patients were non-responders to their neoadjuvant therapy, and all patients also suffered from vital lymph node metastases as an expression of a very high risk of recurrence." (PMID 41300990, 2025).
metastatic melanoma (2 papers, 2021 to 2023). A melanoma that has spread from its primary site to another anatomic site. "No third-line systemic therapies have been proven to extend OS in patients with metastatic melanoma or other advanced ASS1-deficient malignancies." (PMID 33674736, 2021). "Thus, we conducted this pharmacodynamic Phase 1 trial of ADI-PEG20 and cisplatin in patients with pretreated metastatic melanoma or other advanced ASS1-deficient malignancies and the main aims were to evaluate the safety, tolerability and efficacy of this combination treatment." (PMID 33674736, 2021).
multiple myeloma (2 papers, 2023 to 2025). "ASS1 expression in bone marrow biopsy specimens of newly diagnosed multiple myeloma patients is different." (PMID 38053661, 2023). "For hematology malignant diseases, methylation in the CpG island of ASS1 has been detected in 71.7% of multiple myeloma patients and patients with ASS1 methylation were less likely to have bone disease and extramedullary disease." (PMID 38053661, 2023). "We hold the opinion that in multiple myeloma, the use of ADI-PEG20 should be individualized based on ASS1 expression." (PMID 38053661, 2023).
pleural mesothelioma (2 papers, 2016 to 2021). A neoplasm that arises from the mesothelial cells of the pleura. "To measure ASS1 protein expression, we stained 2 sets of tissue microarrays (TMA): one with 88 pleural mesothelioma samples and the other with additional 88 pleural mesotheliomas paired with matched normal tissues." (PMID 26982031, 2016).
soft tissue sarcoma (2 papers, 2016 to 2022). A malignant neoplasm arising from muscle tissue, adipose tissue, blood vessels, fibrous tissue, or other supportive tissues excluding the bones. "Surprisingly, a great majority of tumors (606/701, 86.4%) diagnosed as bone (34/39, 87.2%) or soft tissue sarcomas (STSs; 572/662, 86.4%) showed no signal for ASS1 expression." (PMID 27735949, 2016).
thoracic tumors (2 papers, 2017 to 2022). "The current substudy therefore provides evidence supporting arginine deprivation with pegargiminase in targeting thymidine uptake as a treatment for ASS1-deficient thoracic tumors." (PMID 36082278, 2022). "Patients with ASS1-deficient thoracic tumors were treated for up to six cycles, and treatment was well tolerated overall." (PMID 28388291, 2017).
triple-negative breast carcinoma (2 papers, 2024 to 2025). An invasive breast carcinoma which is negative for expression of estrogen receptor (ER), progesterone receptor (PR), and human epidermal growth factor receptor 2 (HER2). "Argininosuccinate synthase (ASS1) acts as a tumor suppressor in triple-negative breast cancer (TNBC)." (PMID 40598535, 2025).
Acute encephalopathy (1 paper, 2014). "Two new mutations of the ASS1 gene have been identified: p.Met186Arg was identified in homozygosis in one patient of Romanian origin who presented acute encephalopathy “intoxication type” and multiorgan failure in the neonatal period." (PMID 25433810, 2014).
adenoma (1 paper, 2021). A neoplasm arising from the epithelium. "To examine the role of epithelial Ass1 on spontaneous adenoma formation in Apc heterozygous epithelium, we crossed these VillinCreERT2Ass1wt/wt and VillinCreERT2Ass1fl/fl to Apcfl/fl mice." (PMID 34599156, 2021). "In adenomas of wild-type mice, ASS1 protein expression was increased, although not all adenomatous cells expressed high levels of ASS1." (PMID 34599156, 2021). "At 16 weeks after recombination, we did not observe any effect of Ass1 knockout on the amount or size of the adenomas that were formed." (PMID 34599156, 2021).
arthrogryposis (1 paper, 2018). A rare, non-progressive congenital disorder characterized by multiple joint contractures which are present at birth. "AKS presents multiple overlaps with Aase-Smith syndrome 1 (ASS1 [MIM: 147800]) characterized by arthrogryposis, hydrocephalus, Dandy-Walker malformation, talipes equinovarus, cardiac defects, and risks of stillbirth or premature death." (PMID 29290337, 2018).
brain tumors (1 paper, 2022). "We identified increased mRNA levels of ACLY, ASS1 and ODC1 in medulloblastoma primary tumors compared to other pediatric brain tumors, suggesting an increased reliance in medulloblastoma on polyamines, arginine biosynthesis and the TCA cycle/production of acetyl-CoA." (PMID 35267619, 2022).
brucellosis (1 paper, 2024). Brucellosis is a bacterial infection that spreads from animals to people via unpasteurized dairy products or by exposure to contaminated animal products or infected animals. "Based on these discrepancies, we excluded ASS1 from further analysis and combined the remaining five proteins, which demonstrated strong diagnostic efficiency for brucellosis." (PMID 39872944, 2024).
chronic pancreatitis (1 paper, 2017). A chronic inflammatory process causing damage and fibrosis of the pancreatic parenchyma. "The average scores of ASS1 expression were 2.31 in normal pancreatic ductal cells and 2.46 in the proliferating pancreatic ductules of chronic pancreatitis respectively." (PMID 28187218, 2017).
cleft palate (1 paper, 2018). Cleft palate is a fissure type embryopathy that affects the soft and hard palate to varying degrees. "Consistent with the view that AKS and ASS1 have different etiologies, both ASS1-affected families presented individuals affected with cleft palate, a birth defect not present in the 13 KIAA1109 individuals described here, including those at the severe end of the phenotypic spectrum." (PMID 29290337, 2018).
colon adenocarcinoma (1 paper, 2025). "Analysis of the TCGA database using GEPIA revealed that the levels of ASS1 mRNA were considerably elevated in CRC tissues, including colon adenocarcinoma (COAD) and rectum adenocarcinoma (READ), compared to the nearby normal tissues." (PMID 41304979, 2025).
colorectal adenoma (1 paper, 2021). An adenoma that arises from the colon or rectum. "We utilize murine models where Ass1 is specifically deleted from intestinal epithelium as well as human colorectal adenomas and cancer tissue." (PMID 34599156, 2021).
COVID-19 (1 paper, 2023). A disease caused by infection with severe acute respiratory syndrome coronavirus 2. "These proteins either act as positive regulators of cell death (HBG1, HBB, HBD, and HBA1) or are involved in the cellular response to tumor necrosis factor (FABP4, GPD1, THBS1, ASS1, and PCK2), suggesting that apoptosis may be an important cause of heart failure in patients with COVID-19." (PMID 38087340, 2023).
endometrial tumors (1 paper, 2017). "In this study, we reveal a novel association between ASS1 and migration/invasion of endometrial tumors via regulation of mechanistic target of rapamycin complex (mTORC) 1 signaling." (PMID 28358054, 2017).
endometrioid carcinoma (1 paper, 2017). "Based on these findings, it was suggested that the characteristic ASS1 expression pattern at the tumor invasive front in endometrioid carcinoma specimens is the result of enhanced invasion capability of tumor cells with decreased ASS1 expression." (PMID 28358054, 2017). "Finally, we examined ASS1 expression in 74 cases of endometrioid carcinoma clinical specimens by immunohistochemistry." (PMID 28358054, 2017). "The results of immunohistochemistry using endometrioid carcinoma clinical specimens, in which tumor cells with decreased ASS1 expression lined up along the stroma, are consistent with this hypothesis." (PMID 28358054, 2017).
esophageal adenocarcinoma (1 paper, 2025). A malignant tumor with glandular differentiation arising predominantly from Barrett mucosa in the lower third of the esophagus. "To our knowledge, we are the first to report the existence of ASS1-deficient esophageal adenocarcinomas in a cohort consisting solely of this entity." (PMID 41300990, 2025). "In summary, complete ASS1 loss was identified in 6.2% of patients with esophageal adenocarcinoma, with a further 6.2% showing low ASS1 expression (<10% tumor cells)." (PMID 41300990, 2025). "In summary, 6.2% of the esophageal adenocarcinomas showed an ASS1 loss, and 6.2% showed a low ASS1 expression." (PMID 41300990, 2025). "In our study, we found no significant survival difference between patients with ASS1 loss and those with positive ASS1 expression in esophageal adenocarcinoma." (PMID 41300990, 2025). "This study showed that a complete loss of ASS1 expression in tumor cells could be observed in 6.2% of all patients with esophageal adenocarcinoma." (PMID 41300990, 2025). "In this study, we aimed to determine whether ASS1-loss occurs in esophageal adenocarcinoma and to evaluate the prognostic significance of ASS1 expression in this cancer type." (PMID 41300990, 2025). "Therefore, we investigated the prevalence of ASS1 loss in esophageal adenocarcinoma." (PMID 41300990, 2025). "We aimed to assess the frequency of ASS1 downregulation in patients with esophageal adenocarcinoma." (PMID 41300990, 2025). "To identify the most reliable antibody for ASS1 immunohistochemical staining, we compared the staining results of three different antibodies with corresponding RNAScope in situ analyses in a tissue microarray comprising fifty esophageal adenocarcinoma samples." (PMID 41300990, 2025).